AQP4-AS1 (AQP4 antisense RNA 1)
Synonyms: FLJ30507; C18orf16; CHST9-AS1
Gene: Long non-coding RNA gene on chromosome 18 (26,655,505 to 27,190,698, forward strand). Ensembl gene ENSG00000260372.
Gene Ontology:
Biological process: RNA processing; SRP-dependent cotranslational protein targeting to membrane, signal sequence recognition
Cellular component: nucleolus; signal recognition particle, endoplasmic reticulum targeting
Diseases named in the same sentence as AQP4-AS1 in open-access papers:
AQP4-AS1 is named in the same sentence as 1 disease in open-access papers, as found by Europe PMC text mining. Sharing a sentence is not in itself a finding about the gene and the disease. The quoted sentences say what the papers report.
breast carcinoma (1 paper, 2021). "Aquaporin 4 antisense RNA 1 (AQP4-AS1) transcribes a lncRNA with unknown function, which was found related to the risk of gastric and breast cancer." (PMID 34861872, 2021).